RNFT2 (ring finger protein, transmembrane 2)
Description:
E3 ubiquitin-protein ligase that negatively regulates IL3-dependent cellular responses through IL3RA ubiquitination and degradation by the proteasome, having an anti-inflammatory effect.
Synonyms: TMEM118; FLJ14627
Tractability: Antibody: UniProt predicts a signal peptide or a membrane-spanning region. PROTAC: ubiquitination databases record sites on it; its protein half-life has been measured.
Gene: Protein-coding gene on chromosome 12 (116,738,178 to 116,853,631, forward strand). Ensembl gene ENSG00000135119.
Subcellular location: Membrane
Subcellular location (Human Protein Atlas): Nucleoplasm; Cytosol
Gene Ontology:
Molecular function: ubiquitin protein ligase activity
Biological process: positive regulation of ERAD pathway
Cellular component: membrane
Genetic constraint (gnomAD): Loss-of-function variants: 35 observed, 36.67 expected, observed/expected ratio (o/e) 0.95, 90% interval 0.73 to 1.26. The upper end of that interval is the gene's LOEUF score, 1.26, which puts it in group 5 of 6, group 1 being the genes least tolerant of losing a copy. Missense variants: 480 observed, 456.69 expected, observed/expected ratio (o/e) 1.05, 90% interval 0.98 to 1.13. Synonymous variants: 226 observed, 191.59 expected, observed/expected ratio (o/e) 1.18, 90% interval 1.06 to 1.32.
Homologues: Orthologues: chimpanzee RNFT2 (99% identical), dog RNFT2 (95% identical), pig RNFT2 (95% identical), guinea pig RNFT2 (94% identical), mouse Rnft2 (92% identical), macaque RNFT2 (92% identical), rat Rnft2 (91% identical), rabbit RNFT2 (88% identical), tropical clawed frog rnft2 (69% identical), zebrafish rnft2 (66% identical), Drosophila melanogaster CG13605 (27% identical), Caenorhabditis elegans ZC13.1 (20% identical). Paralogues in human: RNFT1 (38% identical).
Diseases named in the same sentence as RNFT2 in open-access papers:
RNFT2 is named in the same sentence as 9 diseases in open-access papers, as found by Europe PMC text mining. Sharing a sentence is not in itself a finding about the gene and the disease. The quoted sentences say what the papers report.
gastric cancer (2 papers, 2022). A primary or metastatic malignant neoplasm involving the stomach. "In the oncology field, the expression of RNFT2 in gastric cancer tissues was found positively associated with poor prognosis and high recurrence rates." (PMID 36199110, 2022).
Alzheimer disease (1 paper, 2023). A progressive, neurodegenerative disease characterized by loss of function and death of nerve cells in several areas of the brain leading to loss of cognitive function such as memory and language. "Further, four genes are correlated with neuropsychiatric traits such as behavioral disorders, panic disorders, or Alzheimer's disease (MYRFL, TNEN132, RNFT2, and PLA2G4A)." (PMID 37337823, 2023).
lung carcinoma (1 paper, 2023). "RNFT2 as an inhibitor of inflammation targeting IL-3 cytokine receptor IL-3Rα degradation, it may play an important role in the innate immune response chain of lung cancer." (PMID 37542549, 2023).
tumor (3 papers, 2022 to 2023). "Besides, we also discovered that the average expressions of two genes, ECT2 and RNFT2, increased concordantly with the tumor stage progression." (PMID 36400805, 2022). "So as a tumor suppressor SNP rs3088107 and an oncogene RNFT2 were identified." (PMID 36199110, 2022). "The mRNA expression levels of STMN1, CLSPN, MDK, RNFT2, PRR11, and RNF157 were significantly increased in HCC tumor tissue; on the contrary, GHR was significantly decreased compared with normal tissues." (PMID 37542549, 2023).
cancer (1 paper, 2022). A tumor composed of atypical neoplastic, often pleomorphic cells that invade other tissues. "So far, studies on the roles of RNFT2 in cancer research is relatively rare." (PMID 36400805, 2022).
RNFT2 also shares sentences with these, for which no sentence is quoted: behavioral disorders (1 paper); bladder cancer (1); panic disorder (1); schizophrenia (1).